MMP2 (matrix metallopeptidase 2)
Diseases named in the same sentence as MMP2 in open-access papers (continued):
Sharing a sentence is not in itself a finding about the gene and the disease.
emphysema (continued). "More recent investigations provide evidence that both, elastase activities, such as MMP-12, and collagenolytic activities, as exerted by MMP-2 and MMP-9, in combination lead to an effective destruction of lung parenchymal tissue that finally results in the generation of emphysema." (PMID 16398938, 2006). "MMP-2 was the most significantly downregulated protein, which is elevated in COPD SAEC, suggesting the possibility that senolytic treatment may protect against airway remodeling and emphysema." (PMID 40357269, 2025). "On the other hand, a study by March used a murine model of cigarette smoke exposure, and although an increase in MMP-2 and MMP-9 activity was observed and emphysema was induced by exposure, NAC treatment failed to mitigate the severity of emphysema." (PMID 38892239, 2024). "Emphysematous lung tissue destruction is frequently attributed to activation of proteolysis and in particular to Matrix metalloproteinase (MMP) activation, yet our data do not support a role for MMP-2 and MMP-9 in the emphysema development in the copper depleted rat." (PMID 22276220, 2012).
endothelial dysfunction (32 papers, 2012 to 2026). In vascular diseases, endothelial dysfunction is a systemic pathological state of the endothelium (the inner lining of blood vessels) and can be broadly defined as an imbalance between vasodilating and vasoconstricting substances produced by (or acting on) the endothelium. "MMP-2 promotes endothelial dysfunction by causing proteolytic degradation of endothelial nitric oxide synthase (eNOS) and its cofactor, heat shock protein 90 (HSP90)." (PMID 37457745, 2023). "Our results show that r-maspin causes endothelial dysfunction such as proliferation, tube formation, NO synthesis and MMP2 expression." (PMID 28962595, 2017). "Genetic factors, including MMP-2 single nucleotide polymorphisms, may influence enzyme expression and exacerbate endothelial dysfunction." (PMID 40718100, 2025). "Accordingly, the present results show increases in systolic blood pressure and decreases in fetal and placental weights, which may be associated with endothelial dysfunction and reduced MMP-2 activity in RUPP compared with the Norm-Preg group." (PMID 37628999, 2023). "We advanced this knowledge by showing that in the rat SHR model, endothelial dysfunction develops along with two other parameters, namely arterial remodelling and activation of latent pro-MMP2." (PMID 39769104, 2024). "The endothelium controls activation of latent pro-MMP2 in physiological conditions via ET-1, and hence stimulated ET-1 production activates latent pro-MMP2 under conditions of endothelial dysfunction." (PMID 39769104, 2024). "MMP-2 is known for its role in regulating vascular smooth muscle cell migration, arterial remodeling and many endothelial dysfunction." (PMID 35223694, 2022). "Curcumin was found to improve endothelial dysfunction by increasing NO bioavailability and decreasing levels of the angiotensin-converting enzymes MMP-2 and MMP-9 in hypertensive rats." (PMID 34444956, 2021). "The significantly increased levels of MMP-2 in women—both in the EO-PE and LO severe PE subgroups—explain the participation of this enzyme in endothelial dysfunction in the second stage of severe PE." (PMID 33381317, 2020). "We evaluated the concentrations of MMPs in patients with symptoms of PE and confirmed a role for MMP-2 in the development of endothelial dysfunction in this specific complication of pregnancy—results that are mirrored by the similar data of Laskowska." (PMID 33381317, 2020). "The significantly elevated level of MMP-2 we obtained in pregnant women—both with EO-PE and LO severe PE—confirmed the development of endothelial dysfunction as an important element in the pathogenesis of polyorganic damage in PE." (PMID 33381317, 2020). "The high SBP, endothelial dysfunction, and altered MMP-2 activity in collagen content can promote artery wall remodeling." (PMID 30133537, 2018). "Taken together, all of these alterations may be responsible for preventing endothelial dysfunction, impairment of MMP-2 activity, increasing collagen I and III deposition and morphological changes in the aortic artery that prevent SBP elevation." (PMID 30133537, 2018). "It has been also suggested that MMP-2 may reflect endothelial dysfunction in preeclamptic pregnancies and may lead to abnormal vasoactive peptides activity and an enhanced vasoconstriction." (PMID 28798935, 2017). "Inhibition of MMP2 by PI16 could therefore have a significant impact on several aspects of vascular pathology beyond endothelial dysfunction, as shown here." (PMID 27996045, 2016). "MMP2 is capable of degrading elastic fibers in aorta, leading to enhanced stiffening, whereas it also contributes to aortic remodeling by increasing endothelial permeability and promoting endothelial dysfunction, which may facilitate vascular inflammation." (PMID 35133978, 2022).
endothelial dysfunction (continued). "Beyond impaired elimination, CKD fosters a pro-inflammatory and pro-oxidative vascular milieu that promotes endothelial dysfunction, upregulates CD146 expression, and enhances its shedding via matrix metalloproteinase (MMP-2 and MMP-9) activation." (PMID 40564089, 2025). "Migrating VSMCs form fibrous caps on plaques by secreting matrix metalloproteinase 2 (MMP2), MMP9, collagen, and elastin, leading to persistent inflammation and endothelial dysfunction." (PMID 38195542, 2024). "MMP-2 and MMP-9 are colocalized in vessel walls and atherosclerotic plaque, being involved in endothelial dysfunction and DM macrovascular complication and vascular remodeling." (PMID 32093214, 2020). "MMP-2 and MMP-9 were upregulated in diabetic CKD arteries and correlated with stiffening and endothelial dysfunction." (PMID 27042350, 2016). "Tryptase activates metalloproteinases (MMP), such as MMP-1, MMP-2 and MMP-3 and procollagenase, and promotes the degradation of lipoproteins and fibronectin, acting as powerful inflammatory stimulus at the endothelial dysfunction." (PMID 26038676, 2015). "Gene expression of MMP-2 and MMP-9 in peripheral blood leukocytes and circulating levels of MMP-2, MMP-9, pro-inflammatory cytokines (TNF-α, IL-6), and endothelial dysfunction markers (Endothelin-1 [ET-1], adhesion molecules) were quantified via qRT-PCR and ELISA." (PMID 41598609, 2026). "Further, the activation, but not expression, of latent pro-MMP2 strongly correlates with the progression of endothelial dysfunction (r2 = 0.87)." (PMID 39769104, 2024). "Decreased NO and oxidative excess may induce matrix metalloproteinases (MMPs), usually MMP-2 and MMP-9, which break down the fibrous cap containing collagen, elastin, and proteoglycans, resulting in endothelial dysfunction." (PMID 25311097, 2014). "The role of MMP-2 in CTEPH has been widely studied, giving evidence of the negative role of MMP-2 through its involvement in ECM remodeling, endothelial dysfunction, smooth muscle cell proliferation, and vascular remodeling." (PMID 39769454, 2024).
triple-negative breast carcinoma (32 papers, 2015 to 2026). An invasive breast carcinoma which is negative for expression of estrogen receptor (ER), progesterone receptor (PR), and human epidermal growth factor receptor 2 (HER2). "The present study indicated the Bicalutamide inhibited the proliferation and invasion process of triple negative breast cancer cells by targeting AR signaling pathway and down-regulating MMP-2/-9 protein expression levels." (PMID 32332626, 2020). "Piperine suppresses the proliferation and migration of triple negative breast cancer cell lines by reducing the levels of MMP-2 secretion." (PMID 32155880, 2020). "Another new study suggests that silibinin inhibits the proliferation, migration, and invasion of triple-negative breast cancer cells by down-regulating the signal of MMP2." (PMID 33115469, 2020). "The Py8119 tumors used in this study represent the highly invasive triple negative breast cancer that have elevated levels of MMP-2 and MMP-9 activity." (PMID 26336058, 2015). "Similarly, in triple-negative breast cancer, piperine inhibited cell migration by downregulating the expression of MMP2 and MMP9." (PMID 36678600, 2023). "In conclusion, this study preliminarily confirmed in vitro that Bicalutamide can inhibit the proliferation and invasion of triple-negative breast cancer by inhibiting the androgen receptor signaling pathway, which is related to the down-regulation of cyclinD1, mmp-2, and mmp-9 related proteins." (PMID 32332626, 2020). "Furthermore, in an in vitro study, BPA increased the migration and invasion of triple-negative breast cancer cells, while it also induced protein expression of matrix metalloproteinase-2 (MMP-2) and MMP-9." (PMID 33066495, 2020). "Additionally, they noticed that the overexpression of GUSBP11 repressed the epithelial-to-mesenchymal transition in the triple-negative breast cancer cell lines by increasing E-cadherin and decreasing the expression of matrix metallopeptidase 2 (MMP2), MMP7, N-cadherin, and vimentin proteins." (PMID 41431719, 2026). "Neoplastic cell migration in triple-negative breast cancer is significantly enhanced by the HDAC8-induced modulation of mesenchymal markers such as matrix metalloproteinases 2 and 9 (MMP-2 and MMP-9), N-cadherin, fibronectin, and vimentin." (PMID 37834214, 2023). "EZH2 inhibits the transcription of TIMP2, which boosts activities of MMP-2 and MMP-9, which in turn increases the invasive activity of triple-negative breast cancer cells." (PMID 35912155, 2022). "In triple negative breast cancer cells (TNBC), we showed that ARF1 controlled mainly the activation of MMP9 and MMP2 through FAK37." (PMID 35680971, 2022). "BB inhibited MMP-2/9 expression through downregulation of TGF-β1, suppressing proliferation and movement of triple negative breast cancer cells (TNBC)." (PMID 34771481, 2021). "Further, we reported another mechanism by which IGF2BP3 knockdown reduced the MMP2 and MMP9 protein levels in OCCC, as shown in triple negative breast cancer before." (PMID 32083017, 2019). "Eugenol-treated cells showed significantly decreased MMP2 and MMP9 expression and an insignificant increase in TIMP1 expression in HER2 positive and triple negative breast cancer cells." (PMID 30518369, 2018). "The expression of HIF-1α, MMP-2, VE-cadherin, and Twist-1 in triple-negative breast cancer cells is higher than that in non-triple-negative breast cancer cells." (PMID 33363175, 2020). "Similarly, co-expression of CD133, MMP2, and MMP9 was also observed in triple-negative breast cancer cells." (PMID 31623313, 2019). "In addition, treatment with 200 ng/ml CCL20 significantly enhanced cell invasion and stimulated the secretion of MMP-2 and MMP-9 in BT549 and HCC38 cell lines, which are basal-like/triple-negative breast cancer cell lines, as is the MDA-MB-231 cell line." (PMID 28851919, 2017).
triple-negative breast carcinoma (continued). "Treatment with CCL20 noticeably promoted cell invasion and the secretion of MMP-2/9 in the basal-like triple-negative breast cancer cell lines, not the luminal." (PMID 28851919, 2017). "Taken together, our results demonstrate that brucine inhibits the migration, invasion, and vasculogenic mimicry in human triple-negative breast cancer cell line MDA-MB-231, which might be through the disruption of cytoskeleton and downregulation of EphA2, MMP-9, and MMP-2." (PMID 30723742, 2019).
acute kidney injury (31 papers, 2012 to 2025). Sudden and sustained deterioration of the kidney function characterized by decreased glomerular filtration rate, increased serum creatinine or oliguria. "Mmp2 has also been found to be involved in tubular repair after acute kidney injury (AKI), and Mmp2 deficiency protects against ischemia-reperfusion AKI." (PMID 26673451, 2015). "Both MMP-2 and MMP-9 are increased perivascular in acute kidney injury, and systemic effects were also proved by high levels of MMP-2 and -9 in extrarenal circulation in chronic renal diseases." (PMID 33671770, 2021). "MMP-2 causes structural alterations in the TBM that promote tubular atrophy, fibrosis, and renal failure." (PMID 28378840, 2017). "At earlier periods, MMP-2 structurally alters the tubular basement membrane, which triggers tubular EMT with resultant tubular atrophy, fibrosis and renal failure." (PMID 27455234, 2016). "In various models of acute kidney injury (AKI), which are mostly produced by renal ischemia-reperfusion injury, not only increased expressions of MMP-2, -9 and TIMP-2, but also decreased expression of TIMP-1 have been observed." (PMID 27455234, 2016). "In the rat renal failure model, UCG showed a renoprotective effect; it could promote extracellular matrix degradation and regulate MMP-2/TIMP-1 balance or signal molecular activity of the TGF-β/Smad pathway to alleviate renal dysfunction and tubulointerstitial fibrosis." (PMID 34678995, 2021).
malignant glioma (30 papers, 1999 to 2025). A grade III or grade IV glioma arising from the central nervous system. "A previous study using a microarray analysis, demonstrated that the increased expression of Mmp2 is involved in invasiveness of malignant glioma, an observation that is consistent with our findings." (PMID 32330152, 2020). "KIF2A knockdown suppresses cell proliferation, cell invasion, and cell migration through regulating matrix metalloproteinases-2 (MMP-2) activity in human malignant glioma cell lines." (PMID 33331418, 2020). "Another study showed that FoxM1 promoted the invasion and disease progression of malignant glioma by enhancing MMP-2 gene transcription." (PMID 30580327, 2018). "MMP2 is recognized as one of the strong cancer-promoting genes which promotes the invasion and metastasis of malignant glioma, and promotes tumor metastasis by degrading the extracellular matrix." (PMID 25872784, 2015). "TIMP-2 is an endogenous MMP-2 inhibitor, and the balance between TIMP-2 and MMP-2 is a critical determinant of malignant glioma invasion." (PMID 26245666, 2015). "In particular, MMP-2 and MMP-9 have been reported to be closely associated with invasion and angiogenesis in malignant gliomas." (PMID 20587068, 2010). "Our findings suggested that HMGA2 and MMP2 may be promising prognostic markers and potential therapy site in malignant gliomas." (PMID 29733521, 2018). "Western blot analysis showed that DHA could upregulate the protein level of RECK as well as downregulate the marker proteins (N-Cadherin and MMP-2) for migration and invasion ability of cancer cells in malignant glioma cells in a dose-dependent manner." (PMID 28208619, 2017). "More highly malignant glioma express increased levels of MMP-2 and MMP-9." (PMID 23613942, 2013). "In malignant gliomas, MMP-2 and MMP-9 are the most abundant forms of MMPs, while the 130 kDa MMP may represent a complex of MMP-9 and tissue inhibitor of matrix metalloproteinase-1, or a dimer of MMP-9." (PMID 18186943, 2008). "The levels of the mRNA and protein of MMP2 were positively correlated with those of HMGA2, further confirming that HMGA2 overexpression promotes the cell invasion of malignant gliomas by directly activating MMP2 expression." (PMID 29733521, 2018). "Over-expression of matrix metallopeptidase 2 (MMP2) and its extracellular activation and pro-invasion function have been widely reported in cancer, including malignant glioma." (PMID 29290950, 2017). "Among those, gelatinase-A (MMP-2), gelatinase-B (MMP-9), and matrix metalloproteinase-14 (MT1-MMP) are involved in different aspects of the pathophysiology of malignant gliomas." (PMID 28629170, 2017). "The inhibition of MACC1 expression suppressed the activity of MMP-2 as well as MMP-9, leading to a decreased capacity for invasion and metastasis in malignant glioma cells." (PMID 26043756, 2015). "EFEMP1 can increase the expression and activity of MMP-2 and MMP-9 in malignant gliomas, a finding which is somewhat similar to the results of our study." (PMID 25987128, 2015). "We also measured MMP-2 and MMP-9 levels in cerebrospinal fluid (CSF) from patients with recurrent malignant gliomas." (PMID 18186943, 2008).
malignant glioma (continued). "MMP-2 and MMP-9 are the most abundant forms of MMPs in malignant gliomas, while a 130 kDa MMP is thought to be MMP-9 complexed to other proteinases." (PMID 18186943, 2008). "This gene can induce transforming growth factor beta 1 (TGF-β) signaling, followed by nuclear factor kappa B (NF-κB) mediated matrix metallopeptidase 2/9 (MMP2/9) overexpression orchestrating migration, invasion and epithelial–mesenchymal transition in malignant glioma cells of human origin." (PMID 37335084, 2023). "To examine whether our selective clones could selectively inhibit the activity of MMP14 in a cancer cell model, we performed a gelatin zymography assay with U87-malignant glioma (U87MG) cells, which naturally express high levels of MMP14, MMP9 and MMP2." (PMID 30174795, 2018). "Our results showed that the expression of TIMP-2 was not changed, while MMP-2 activity increased depending on the radiation dose in malignant glioma cell lines." (PMID 26245666, 2015). "In summary, we revealed previously unknown mechanisms of gliomagenesis and malignant progression driven by HMGA2 via direct activation of the transcription of the MMP2 gene, the HMGA2/GCN5 epigenetic regulation axis may provide novel targeting site in malignant glioma therapy." (PMID 29733521, 2018). "We found that the expression levels of MMP‐2, MMP‐9, ZEB1, N-cadherin, and Integrin β1 significantly diminished in the siRNA1-RACK1 and siRNA2-RACK1 groups, suggesting that siRNA-RACK1 might suppress migration and invasion of malignant glioma cells by inhibiting the EMT signaling pathway." (PMID 27763568, 2016).